CEP104 (centrosomal protein 104)
Description:
Required for ciliogenesis and for structural integrity at the ciliary tip.
Synonyms: KIAA0562; GlyBP; RP1-286D6.4; CFAP256; ROC22; JBTS25; MRT77
Tractability: PROTAC: ubiquitination databases record sites on it.
Gene: Protein-coding gene on chromosome 1 (3,812,086 to 3,857,723, reverse strand). Ensembl gene ENSG00000116198.
Subcellular location: Cell projection, cilium; Cytoplasm, cytoskeleton, microtubule organizing center, centrosome, centriole; Cytoplasm, cytoskeleton, microtubule organizing center, centrosome; Cytoplasm, cytoskeleton, spindle pole
Gene Ontology:
Molecular function: identical protein binding; protein binding
Cellular component: centriole; cilium; centrosome; spindle pole
Genetic constraint (gnomAD): Loss-of-function variants: 73 observed, 104.24 expected, observed/expected ratio (o/e) 0.7, 90% interval 0.58 to 0.85. The upper end of that interval is the gene's LOEUF score, 0.85, which puts it in group 3 of 6, group 1 being the genes least tolerant of losing a copy. Missense variants: 988 observed, 1,126.7 expected, observed/expected ratio (o/e) 0.88, 90% interval 0.83 to 0.92. Synonymous variants: 365 observed, 413.86 expected, observed/expected ratio (o/e) 0.88, 90% interval 0.81 to 0.96.
Gene-disease validity (ClinGen):
ClinGen rates the evidence that CEP104 causes each of these diseases.
ciliopathy (autosomal recessive): Definitive. A genetic disorder of the cellular cilia or the cilia anchoring structures, the basal bodies, or of ciliary function.
Homologues: Orthologues: chimpanzee CEP104 (99% identical), macaque CEP104 (97% identical), dog CEP104 (82% identical), rat Cep104 (81% identical), mouse Cep104 (81% identical), guinea pig CEP104 (79% identical), pig CEP104 (79% identical), tropical clawed frog cep104 (68% identical), rabbit CEP104 (58% identical), zebrafish cep104 (52% identical), Drosophila melanogaster CG10137 (30% identical), Caenorhabditis elegans T06D8.2 (15% identical), and 3 more.
Diseases named in the same sentence as CEP104 in open-access papers:
CEP104 is named in the same sentence as 10 diseases in open-access papers, as found by Europe PMC text mining. Sharing a sentence is not in itself a finding about the gene and the disease. The quoted sentences say what the papers report.
Joubert syndrome (9 papers, 2017 to 2025). Joubert syndrome (JS) is characterized by congenital malformation of the brainstem and agenesis or hypoplasia of the cerebellar vermis leading to an abnormal respiratory pattern, nystagmus, hypotonia, ataxia, and delay in achieving motor milestones. "Human CEP104 variants were shown to cause Joubert syndrome (JBTS), a recessive neurodevelopmental ciliopathy, which may be due to aberrant hedgehog signaling." (PMID 39889304, 2025). "Furthermore, Cep104 mutations are linked to Joubert syndrome, a genetically heterogeneous ciliopathy." (PMID 28017521, 2017). "Moreover, CCDC66 is part of a ciliary tip module that includes other MAPs such as CEP104, CSPP1, TOGARAM1 and ARMC9, which are mutated in the Joubert syndrome." (PMID 40729374, 2025). "Moreover, the interactome contained components of the CCDC66-linked Joubert syndrome module, such as ARMC9, TOGARAM1, CEP104 and CSPP1, known for their roles in cilium length regulation." (PMID 40729374, 2025). "Here we reconstituted in vitro the individual and collective activities of the ciliary tip module proteins CEP104, CSPP1, TOGARAM1, ARMC9 and CCDC66, which interact with each other and with microtubules and, when mutated in humans, cause ciliopathies such as Joubert syndrome." (PMID 39856351, 2025). "A biallelic defect of CEP104 causes Joubert syndrome, but no clinical syndrome has been discovered caused by a CROCC or TSD2 variant." (PMID 34194391, 2021). "The remaining novel variants were: CCDC39:p.Glu598* (CADD, 37); CCDC40:c.1097delT (frameshift); CEP104:p.Glu698Lys (Joubert syndrome 25, Patient 9); DNAAF5:p.Val431Ala (Condel: 0.886); DNAH5 duplication of exon 1–48 (unknown significance); HYDIN:p.Pro3213Arg (likely pathogenic, Patients 17–18)." (PMID 34768622, 2021).
ciliopathies (3 papers, 2017 to 2025). "Our findings reveal a novel link between ciliopathy-associated proteins and suggest a model of how Cep104 activity at microtubule ends is tied to ciliogenesis." (PMID 28017521, 2017). "The authors also found that the ciliopathy-associated Nek1 kinase binds to Cep104 and that the centriole-capping protein CP110 competes for this binding." (PMID 28017521, 2017).
developmental delay (1 paper, 2019). "In this study, we report a Chinese boy with CEP104 mutations presenting with symptoms consistent with JS, displaying global developmental delay, facial dysmorphism, oculomotor apraxia, and hypotonia." (PMID 31625690, 2019).
growth disorder (1 paper, 2021). "Loss of function of the two other ciliary genes (CEP104 and CROCC) or TSTD2 has not been reported to be associated with a growth disorder, although CROCC has been detected at genome-wide significance for adult height." (PMID 34194391, 2021).
tumor (2 papers, 2017 to 2019). "Here we provide structural and biochemical data that Cep104 contains a tubulin-binding TOG (tumor overexpressed gene) domain and a novel C2HC zinc finger array." (PMID 28017521, 2017).
CEP104 also shares sentences with these, for which no sentence is quoted: infection (3 papers); gastric cancer (1); hepatocellular carcinoma (1); Oculomotor apraxia (1); retinal diseases (1).